TF (transferrin)
Diseases named in the same sentence as TF in open-access papers (continued):
Sharing a sentence is not in itself a finding about the gene and the disease.
liver cirrhosis (16 papers, 2010 to 2025). "We present an interesting case of severe alcoholic hepatitis mimicking HH with severely elevated ferritin levels and transferrin saturation with underlying liver cirrhosis." (PMID 37575743, 2023). "HH is one of the common causes of iron overload disorders and usually presents with liver cirrhosis in a setting of significantly elevated ferritin and elevated transferrin saturation." (PMID 37575743, 2023). "Fe2+ accumulation and lipid peroxidation exist in patients with liver cirrhosis, but the expression level of TF is low." (PMID 40938883, 2025). "A pathway enrichment analysis of our gene expression profiling of OX40+ Tregs, from human liver cirrhosis/tumor (CT) samples, uncovered transferrin endocytosis and recycling among pathways specifically upregulated in CT OX40+ Tregs." (PMID 38954474, 2024). "For further analysis of iron, ferritin, and transferrin, patients with liver cirrhosis were excluded." (PMID 39200147, 2024). "Patients with liver cirrhosis tended to have higher ferritin, to have significantly higher iron and reduced transferrin levels." (PMID 39200147, 2024). "The cohort included 28 patients with liver cirrhosis, who often have high ferritin and low transferrin levels." (PMID 39200147, 2024). "IL-17A had been reported to be involved in vascular inflammation, induce endothelial cell activation, and further up-regulate endothelial TF expression in liver cirrhosis." (PMID 37063881, 2023). "Patients with liver cirrhosis were shown to have reduced hepatic TF and increased hepatic iron levels suggesting that TF has a protective role in these contexts." (PMID 33499222, 2021). "Patients with liver cirrhosis have reduced levels of hepatic TF and increased levels of hepatic iron, supporting the idea of a protective role for hepatic TF in maintaining liver function." (PMID 33117818, 2020). "Additionally, another six genes (ALB, APOH, FABP1, FGB, FGG, and TF) were identified from our previous HCC EV-specific gene panel given their performance in distinguishing early-stage HCC from liver cirrhosis." (PMID 40307890, 2025). "Hepcidin increases in parallel with ferritin in healthy women and is affected by liver cirrhosis and inflammation; it currently does not provide further diagnostic value over ferritin, iron, and transferrin levels." (PMID 39200147, 2024). "Similarly, patients with liver cirrhosis were shown to have lower serum and hepatic transferrin, resulting in iron overloading and ferroptosis in multiple organs." (PMID 38397002, 2024). "However, in liver cirrhosis (alcoholic and nonalcoholic origin) and in toxic hepatitis the changes were limited to one transferrin isoform." (PMID 32911601, 2020). "However, serum albumin (17.9 ± 4.4 vs 24.1 ± 6.0 g/L, p = 0.001) and transferrin (1.3 ± 0.6 vs 2.0 ± 0.5 g/L, p < 0.0001) levels were demonstrated to be significantly lower in patients with Child-Pugh C liver cirrhosis compared to those with Child-Pugh B disease." (PMID 20576106, 2010).
microcytic anemia (16 papers, 2010 to 2024). Anemia in which the red blood cell volume is decreased. "Low transferrin concentration leads to microcytic anemia by deficient iron transport from the peripheral tissues (mainly the liver) to the bone marrow." (PMID 38355710, 2024). "Similarly, patients with IRIDA have an autosomal recessive mutation in the gene encoding TMPRSS6 resulting in hypochromic microcytic anemia, low serum transferrin saturation, and inappropriately elevated hepcidin concentrations." (PMID 20631898, 2010). "Hypochromic microcytic anemia was present at one month of age, with a concomitant increase in serum iron levels and transferrin saturation." (PMID 35457224, 2022). "Such patients present with severe microcytic anemia, profound hypoferremia, low transferrin saturation, elevated hepcidin levels, and negligible responses to oral iron replacement therapy." (PMID 36254154, 2022). "We report IRIDA in fraternal twins who presented with severe microcytic anemia, hypoferremia, hypoferritinemia, and low transferrin saturation states." (PMID 36254154, 2022). "These mice exhibit hypochromic microcytic anemia, low transferrin levels, severe growth retardation and a robust response to mouse plasma or purified transferrin injections, a pattern of characteristics reminiscent of human congenital hypotransferrinemia." (PMID 20631898, 2010). "Besides increased hepcidin levels, the main features of IRIDA typically include moderate/severe microcytic anemia, low transferrin saturation and paradoxically normal to slightly increased ferritin levels, without signs of inflammation." (PMID 34343368, 2021). "Regarding the 17 patients with microcytic anemia, 14 showed low iron with low/normal transferrin." (PMID 33256142, 2020). "Both disorders are characterized by microcytic anemia and variable transferrin saturations." (PMID 21936912, 2011). "The role of transferrin is highlighted in the congenital atransferrinemia/hypotransferrinemia characterized by hypochromic, microcytic anemia and hemosiderosis, in which the body fails to produce enough functional transferrin, i.e., mutation in transferrin (TF) gene." (PMID 36140091, 2022). "The typical features of this disorder are hypochromic, microcytic anemia with a very low mean corpuscular volume of erythrocytes, low transferrin saturation, no (or inadequate) response to oral iron, and only a partial response to parenteral iron." (PMID 25805669, 2015).
coronary artery disease (15 papers, 2013 to 2025). "TF-CAS patients were more likely to have coronary artery disease (P = .02), hyperlipidemia (P < .001), and COPD (P < .001)." (PMID 37852227, 2024). "In this study, to better understand the mechanism of CTSD/CTSB in sudden coronary heart disease death, we also analyzed the TF-mRNA-miRNA relationship to obtain the co-regulatory network." (PMID 33964876, 2021). "Therefore, this study aimed to explore the association between hemoglobin, serum iron, transferrin, TIBC, transferrin saturation, ferritin, and mortality risk among CAD patients recruited from the Guangdong coronary artery disease cohort (GCADC)." (PMID 39796572, 2024). "Transferrin saturation (TS) is associated with mortality across populations, but its nonlinear relationship with all-cause mortality in coronary artery disease (CAD) and the role of systemic inflammation remain unclear." (PMID 40455700, 2025). "In conclusion, our study reveals a significant nonlinear, U-shaped relationship between transferrin saturation (TS) and all-cause mortality in patients with coronary artery disease (CAD), with an inflection point at 30.5%." (PMID 40455700, 2025). "In addition, a meta-analysis of prospective studies demonstrated a negative relationship between transferrin saturation and cardiovascular events such as coronary heart disease and acute myocardial infarction." (PMID 30755213, 2019).
hypercoagulability (15 papers, 2010 to 2025). "The success of these interventions is particularly noteworthy because hypoxia and low temperature can induce hypercoagulability at high altitudes by mechanisms such as upregulating transferrin, thereby increasing the risk of venous thromboembolism." (PMID 39465135, 2024). "TBI-associated hypercoagulability is associated with injury-mediated disruption of the cerebrovasculature with exposure of abundant subendothelial TF to circulating factor VII initiating the extrinsic pathway." (PMID 20082712, 2010). "Notably, many studies suggested that high levels of TF expression were observed in different types of cancer, and the level of TF expression was associated with tumor progression and hypercoagulability." (PMID 37940761, 2024). "LPS may also cause hypercoagulation via tissue factor-(TF-) mediated activation of hemostasis in whole blood samples from adults and neonates." (PMID 26462180, 2015). "Enzymatic hypercoagulability, hyperfibrinogenemia, and intravascular TF expression have been identified in dogs with IMHA as contributory factors to development of pathologic thrombosis." (PMID 40538729, 2025). "Enzymatic activities of thrombin and FXIIa were elevated and APTT, PT, and tail bleeding time were shortened upon transferrin overexpression, suggesting a hypercoagulability state." (PMID 31811276, 2020). "Patients with CKD exhibit a hypercoagulable state, which can be represented by elevated concentrations of hemostatic parameters like TF/VII, PAI-1, and fibrinogen." (PMID 30546314, 2018). "A changed iron profile (e.g. low transferrin and/or high serum ferritin) is also central to thrombosis and hypercoagulation and iron dysregulation is heavily implicated in AD." (PMID 26462180, 2015). "However, a recent study found that ID-induced upregulation of transferrin levels and iron-binding ability can induce hypercoagulability by deactivating antithrombin through the thrombin/Factor XIIa complex." (PMID 35067842, 2022). "Overall, patients with stable COPD exhibit major alterations of fibrinogen, FII, FV, FVII, FVIII, FIX, D-dimers, von Willebrand factor Ag, von Willebrand factor Ac, TF, TAT, FPA, β-thromboglobulin, tPA-PAI, prothrombin fragment 1 and 2, and maximum thrombin levels, pointing to hypercoagulability." (PMID 34441381, 2021). "With respect to hypercoagulability, patients with T1DM were reported to have elevated circulating tissue factor procoagulant activity (TF-PCA) and plasma coagulation factor VIIIa, and the mechanism regulating TF-PCA in T1DM might not be the same as in T2DM." (PMID 31935226, 2020).
Hyperglycemia (15 papers, 2015 to 2025). An increased concentration of glucose in the blood. "Our results have confirmed pervious results that showed ferritin and transferrin levels, despite being negatively associated, were independently and positively associated with hyperinsulinemia and hyperglycaemia." (PMID 38715055, 2024). "Hyperglycemia causes glycosylation of transferrin and ferritin which reduces their iron-binding capacity, thus increasing free iron levels." (PMID 35155019, 2022). "For example, hyperglycemia, diabetic ketoacidosis and other forms of acidosis predispose the host to mucormycosis because of compromised ability of transferrin to chelate iron, thereby making iron available to invading organisms." (PMID 25974051, 2015). "This study demonstrated that altered expression of these TF genes could be associated with hyperglycemia-induced nephropathy and, thus, aids in understanding the molecular drivers, essential genes, and pathways that trigger DN initiation and development." (PMID 36659918, 2023). "Furthermore, hyperglycemia leads to glycosylation of transferrin and ferritin, reducing the iron binding capacity and causing increase in free iron." (PMID 37151941, 2023). "We report that hyperglycemia-induced altered gene expression of the key TF genes leads to morphological abnormalities in zebrafish glomeruli, pronephric tubules, proximal and distal ducts." (PMID 36659918, 2023). "We have seen that H3K4me3 levels were increased due to elevated O-GlcNAc levels at D30 and D49 of neural differentiation and also due to maternal hyperglycemia at the neurogenic TF gene promoters." (PMID 35470239, 2022). "In a DKA host, the released iron from transferrin due to hyperglycemia and acidification of the milieu is also transported by the Ftr1p because R. delemar mutants with reduced expression of Ftr1p have defective virulence in DKA mice." (PMID 28771587, 2017). "Hyperglycemia can induce excessive glycosylation of proteins such as transferrin and ferritin, diminishing their iron affinity." (PMID 28771587, 2017). "Fob1 and Fob2 are likely dispensable in the DKA model since Fe3+ is released from transferrin by the action of acidosis and hyperglycemia and transported into the fungal cell via the Ftr1p." (PMID 25974051, 2015). "Hyperglycemia leads to glycosylation of transferrin and ferritin and reduces iron binding." (PMID 35330225, 2022). "In the present study, the associations of multiple iron metabolism biomarkers, including SF, transferrin, sTfR, TSAT, SI, TBI, and sTfR-F-index, with IGM, T2DM, and hyperglycemia were investigated." (PMID 37111154, 2023). "The results of this study showed that serum iron, serum ferritin, and transferrin saturation in GDM patients increased, which may be due to the continuous hyperglycemia of GDM patients affecting the change in iron metabolism, and promoting the deposition of iron in the body." (PMID 32513913, 2020).
iron (15 papers, 2012 to 2025). "This suggests that TI patients may still be at risk for iron related cardiac dysfunction through exposure to non-transferrin bound iron." (PMID 25495194, 2014). "Circulating NTBI usually increases when the binding capacity of transferrin is exceeded (iron overload)." (PMID 39666728, 2024). "Transferrin saturation positively correlated with the units of blood transfusion, suggesting its role as an indicator of iron overload." (PMID 39262540, 2024). "Similarly, SNPs in genes regulating iron homeostasis, such as HFE and TF, could interact with high vitamin C intake to exacerbate oxidative damage through increased ROS production and iron overload in renal tissues." (PMID 40514697, 2025). "Thus elevated non-transferrin bound serum iron level may lead to cardiomyocyte iron overload accompanied by Ca2+ overload, both impairing cardiomyocyte Ca2+ handling and contractile function." (PMID 30361476, 2018). "Follicular-fluid transferrin levels in stage III/IV EM infertility significantly decreased, ferric ion levels increased, and iron overload existed." (PMID 36082180, 2022). "A study of 39 patients with T1D patients and 100 controls, found that patients had lower total iron binding capacity, lower transferrin, and higher haptoglobin levels, but found no sign of iron overload." (PMID 29113123, 2017). "This also explains some of the phenotypic characteristics of the syndrome: normal transferrin saturation, increased iron accumulation in macrophages and absence of progression of iron overload." (PMID 22586470, 2012). "Thus, iron which is bound to transferrin is prevented from entering the cell and therefore mice lacking β2-M of HFE have increased iron overload." (PMID 23874600, 2013).
diabetic nephropathy (14 papers, 2015 to 2025). "In addition, our results suggest that either the urinary transferrin or the urinary/index transferrin ratio are useful to identify patients with diabetic nephropathy at early risk for ED/vascular damage." (PMID 34743740, 2021). "For instance, renal biopsies from patients with diabetic nephropathy show increased transferrin expression and iron deposition in renal tubular epithelial cells compared to healthy controls." (PMID 41139808, 2025). "Early diabetic nephropathy is characterised by a pathological increase in glomerular permeability; then then albumin and other plasma proteins like transferrin, leak from the plasma into the urine." (PMID 34743740, 2021). "This case–control study aimed to evaluate the relation between ED and urine transferrin, even before early diabetic nephropathy is present." (PMID 34743740, 2021). "The lead candidate is urinary transferrin which has been claimed to be more sensitive than microalbuminuria as a predictor of diabetic nephropathy." (PMID 32665774, 2020). "Out of the tested biomarkers, urinary transferrin, urinary Retinol binding protein (RBP) and serum osteopontin had the best diagnostic value for diabetic nephropathy presence based on the AUC value." (PMID 28577020, 2017). "Differing from albumin in terms of their molecular radii and isoelectric points, urinary ceruloplasmin and TF have been shown to predict the onset of microalbuminuria in diabetic nephropathy." (PMID 27590021, 2017). "Urinary transferrin has shown a gradual significant increase with diabetic nephropathy progression and had significant correlation positively with ACR, while negatively with eGFR." (PMID 28577020, 2017). "Urinary transferrin is upregulated in many diseases such as diabetic nephropathy, IgA nephropathy, ureteropelvic junction obstruction and bladder cancer." (PMID 25789206, 2015). "Transferrin has a molecular weight comparable to albumin, whereas transferrinuria and microalbuminuria in a 24-h urine sample may comparably reflect early diabetic nephropathy." (PMID 34743740, 2021). "Although albuminuria remains one of the most significant predictors of renal decline, other markers, such as serum and urine NGAL, serum cystatin C, urine KIM-1, IgG, and transferrin, may add to the early diagnosis of diabetic kidney disease." (PMID 30158836, 2018). "In humans with diabetic nephropathy, the urinary ALB was related to urinary TF, and urinary TF significantly increased with respect to the progression of glomerular diffuse lesions." (PMID 36855344, 2023). "Previous studies have shown that advanced glycation end modified transferrin (AGE-Tf) levels in diabetic rat kidney tissues were increased; however, its role in diabetic nephropathy remains unclear." (PMID 36778593, 2022). "Whereas transferrin metabolism is related with ED during very early diabetic nephropathy has not been elucidated yet." (PMID 34743740, 2021).
alcohol dependence (13 papers, 2008 to 2025). Physical and psychological dependence on alcohol. "Low-carbohydrate isoforms of transferrin (CDT–Carbohydrate Deficient Transferrin), i.e., desialized transferrin, is a well-known, highly sensitive, and specific test (82% and 97%, respectively) in the diagnosis of alcohol dependence." (PMID 36983134, 2023). "A French study showed that 80% of acute ethanol poisonings had elevated γ-glutamyltransferase and carbohydrate-deficient transferrin values, indicating harmful alcohol consumption over some time, suggesting that these patients should be offered treatment for alcoholism." (PMID 19025643, 2008). "Traditionally, with alcohol dependence, we link aspartate aminotransferase (AST), carbohydrate-deficient transferrin (CDT), mean cell volume (MCV), alanine aminotransferase (ALT), and γ-glutamyl transferase (GGT)." (PMID 36983134, 2023). "The demonstration of the relationship between alcohol consumption and abnormal transferrin glycosylation dates back to 1979 and was the first commercial glycomic marker of alcohol abuse (CDT, carbohydrate-deficient transferrin)." (PMID 35204742, 2022). "We present a case where a simple heterozygote with alcoholism developed high ferritin and high transferrin saturation indicative of iron overload." (PMID 33596964, 2021). "As salivary transferrin is suggested to be potential marker of alcohol dependence or chronic alcohol drinking, we investigated if changes in transferrin glycosylation would result in a real formation of the salivary alcohol marker CDT." (PMID 33334005, 2020). "Serum carbohydrate-deficient transferrin (CDT), an 80 kDa glycoprotein, is one of the most commonly employed biomarkers to detect alcohol dependence." (PMID 33334005, 2020). "Low-carbohydrate isoforms of transferrin (CDT, carbohydrate-deficient transferrin), specifically desialylated transferrin, are well known for their high sensitivity and specificity (82% and 97%, respectively) in diagnosing alcohol dependence." (PMID 39063626, 2024). "Further analyses need to determine whether these findings from rats also apply to humans and whether transferrin can indeed serve as a reliable biomarker for alcoholism." (PMID 23584750, 2008).